RN7SL73P (RNA, 7SL, cytoplasmic 73, pseudogene)
Gene: Miscellaneous RNA gene on chromosome 3 (195,553,792 to 195,554,043, forward strand). Ensembl gene ENSG00000265882.
Homologues: Paralogues in human: Metazoa_SRP (88% identical), Metazoa_SRP (77% identical), Metazoa_SRP (70% identical), Metazoa_SRP (68% identical), RN7SL605P (67% identical), Metazoa_SRP (65% identical), Metazoa_SRP (64% identical), Metazoa_SRP (63% identical), Metazoa_SRP (62% identical), Metazoa_SRP (60% identical), RN7SL455P (60% identical), RN7SL531P (60% identical), and 706 more.